BRCA1 (BRCA1 DNA repair associated)
Diseases named in the same sentence as BRCA1 in open-access papers (continued):
Sharing a sentence is not in itself a finding about the gene and the disease.
cancer (continued). "Upregulation of multiple members of gene networks involved in cell cycle, DNA repair, and cancer was observed, including upregulation of BRCA1 and 2, and BIRC5 (Survivin) genes." (PMID 25632947, 2015). "We focused on identifying mutations in BRCA1, BRCA2 and PALB2 and the CHEK2 c.1100delC mutation, as the risks for the development of breast and associated cancers with these genes have been determined by analysing large study populations." (PMID 26577449, 2015). "Taken together, these results suggested the screening of BRCA1/2 mutation carrier using NGS has a role in aiding cancer prevention and reducing the cancer risk in unaffected individuals." (PMID 25802882, 2015). "Research has subsequently evolved into the connection of BRCA1/2 with cancers at other sites within the body." (PMID 26236408, 2015). "miRNA expression was assessed in 11 BRCA1 basal, 16 sporadic basal, 17 luminal grade 3 cancers via microarrays." (PMID 26152113, 2015). "We found very low average levels of methylation in the BRCA1 promoter region in all samples (1.4, 1.6 and 3 % for control mammoplasty, adjacent and cancer samples, respectively) including a few outliers with considerable methylation." (PMID 26510686, 2015). "Our studies further suggest that synthetic lethality interaction (PARP1 and BRCA1/BRCA2) only exist in certain types of cancers." (PMID 25865228, 2015). "As a solo agent, rucaparib has been demonstrated to sensitize human cancer cells or xenograft tumours with mutated or epigenetically silenced BRCA1/2, indicating a potential role for PARP inhibitors in sporadic human cancers." (PMID 26610585, 2015). "The predicted targets of the top 32 miRNAs differentially expressed between BRCA1 and basal cancers (excluding mir-892, −190b and 590-3p) were sought via a union search of miRBase and TargetScan." (PMID 26152113, 2015). "A review of the BRCA1 and BRCA2 mutation spectrum found in French Canadian cancer families where comprehensive analysis was performed supports this strategy." (PMID 25884701, 2015). "In conclusion, this study is the first attempt to define the autoantibodies to synthetic lethal interactions (PARP1 and BRCA1/2) which would be useful in developing therapeutic targets for treatment of certain types of cancer." (PMID 25865228, 2015). "Women who accept predictive BRCA1/2 genetic testing tend to have significantly higher levels of cancer worry than women who decline testing." (PMID 25391615, 2015). "This was as a result of the subgroup analysis of BRCA1/2 mutant cancers (germline or somatic), in the molecularly unselected Study 19 of relapsed platinum sensitive high-grade serous ovarian cancer." (PMID 26557500, 2015). "Selection of miRNAs was based on the top 75 miRNAs (based on fold change) differentiating between basal and luminal cancers and between BRCA1 and sporadic basal cancers." (PMID 26152113, 2015). "In line with this, the current study demonstrated TRs to be expressed in 9 out of 12 triple negative cancers and to be highly sensitive to TR modulation in triple negative, BRCA1 mutant HCC3153." (PMID 26029931, 2015). "Actually, hereditary breast cancer with genomic aberration in BRCA1 is a type of cancer with defects in the DNA repair pathway." (PMID 25636033, 2015).
cancer (continued). "Nonetheless, several gene sets with potential importance for cancer development are enriched such as genes positively correlated with BRCA1, ATM, and CHEK2 expression across normal tissues (GSEA, q < 10-28)." (PMID 25768983, 2015). "The expression of Cyclin D1, FOXP1, FIH-1, pan-ERβ, NRP1 and CD99, predicted to be regulated by BRCA1 specific miRNAs by computer prediction algorithms, was assessed via immunohistochemistry in a cohort of 35 BRCA1 and 52 sporadic basal-like cancers." (PMID 26152113, 2015). "Genetic abnormalities occur in all cancers therefore, as BRCA1/2 pathways safeguard genetic content they are seen as critically important in research." (PMID 26236408, 2015). "In this study, at one end of the spectrum, there is a subgroup composed entirely of 10 BRCA1 cancers, at the opposite end there is a cluster entirely composed of 11 sporadic cancers, which has a pattern of miRNA expression resembling in vitro basal cell lines." (PMID 26152113, 2015). "A cluster analysis based on the top 100 miRNAs discriminating between BRCA1 and sporadic basal cancers was performed on all basal samples (including cell lines)." (PMID 26152113, 2015). "Unsupervised clustering of basal cancers resulted in a “sporadic” cluster of 11 cancers, and a “BRCA1” cluster of 16 cancers, including a subgroup composed entirely of 10 BRCA1 cancers." (PMID 26152113, 2015). "The 7 CGC genes that were detected by SomInaClust only included well-known (germline) cancer genes such as BRCA1, MEN1 and NF1." (PMID 25903787, 2015). "It is also worth mentioning that the inactivation of 53BP1 was shown to potentiate homologous recombination and increase DNA damage tolerance of cancer-prone BRCA1 -/- cells, with severe implications for therapeutic treatments." (PMID 25569305, 2015). "BRCA1 methylation was low for all three tissue types, ranging from a mean of 1 % in adjacent to only 3 % in cancer samples." (PMID 26510686, 2015). "Collectively, these findings suggest that breast epithelial cells in tissues of BRCA1-mutation carriers also exhibit misregulation of SIRT1 expression as well as DDR and pRb pathway activation before the onset of cancer." (PMID 26106036, 2015). "Our results reveal a model for the BRCA1-miR-593-5p–MFF axis in mediating mitochondrial fission in cancer cells." (PMID 25912308, 2015). "From whole-genome sequences of over 1000 HCC cases entered into the Catalogue of Somatic Mutations in Cancer (COSMIC) database, rates of BRCA1 and BRCA2 mutations were 0.07 and 1.7 %, respectively." (PMID 26449224, 2015). "The breast cancer-associated protein, BARD1 (BRCA1-associated RING domain protein), co-localizes with BRCA1 in nuclear foci." (PMID 26402707, 2015). "In a three-dimensional plot generated from an exploratory principle component analysis, the BRCA1 cancers formed a small cluster within a larger cluster incorporating all basal cancers." (PMID 26152113, 2015). "The increasingly recognized involvement of germline mutations in BRCA1 and BRCA2 in diverse cancers, as well as the active design of targeted therapies, further adds to the need to recruit minority subjects." (PMID 26543556, 2015). "Risk models that incorporate both BRCA1 and BRCA2 mutations and other sources of variation are required to provide accurate estimates of mutation carrier probabilities and cancer risk for use in genetic counselling." (PMID 26025000, 2015).
cancer (continued). "Recently, PARP inhibitors have been reported as being specifically applicable to the treatment of BRCA1/2-defective cancers." (PMID 25823848, 2015). "This resulted in a list of 1218 genes predicted to be up and down regulated in BRCA1 basal cancers by miRNAs." (PMID 26152113, 2015). "Carcinomas from Patients M and N cluster together and both have high HRD score and homozygous somatic mutations in BRCA2 and BRCA1, respectively." (PMID 25916844, 2015). "Another important gene in cancer, BRCA1, is involved in mitosis and also plays a key role in the repair of DNA damage." (PMID 24591771, 2014). "Women with germ-line heterozygous mutations in either BRCA1 or BRCA2 genes has been shown to be at increased risk of developing breast, ovarian and also other cancers." (PMID 25594033, 2014). "Median age of diagnosis was 50 years for the non-BRCA1/2 patients compared to 42 years (BRCA1) and 43.5 years (BRCA2) for mutation carriers and 61 years for sporadic cancer patients." (PMID 24479546, 2014). "Amongst 80 cancer patients for whom FMR1 data were available, only 27 (33.8%) were BRCA-positive, 21 carriers of BRCA1 and 6 of BRCA2 mutations." (PMID 25036526, 2014). "The objective of our study was to address specific contributions of BRCA1 to the metabolic features of cancer cells, including the so-called “Warburg effect”." (PMID 25010005, 2014). "Further mechanistic studies are needed in order to understand the precise molecular mechanisms for the effective treatment of cancers with PTEN/BRCA1 signal alterations." (PMID 25426449, 2014). "The successful use of a PARP1 inhibitor for the treatment of tumor cells in which BRCA1 or BRCA2 is inactivated has provided a paradigm for the therapeutic exploitation of cancer cell addiction to a specific DNA repair pathway." (PMID 24618719, 2014). "Genetic depletion or pharmacological inhibition of CDK1 sensitized BRCA1-proficient cancer cell lines to cisplatin and PARPi." (PMID 24624361, 2014). "Particularly, an inverse relationship between ALDH1A1 expression and BRCA1 is noteworthy in the context of studying cancer stem-like cells and chemoresistance." (PMID 25216266, 2014). "The role of BRCA1 in DNA damage response is also a major altered pathway and is consistent with the many genes playing a role in cancer functions." (PMID 25181051, 2014). "We have shown that 14.2% of BC patients and 9.1% of cancer-free females (carriers) harbored methylated BRCA1 promoter in their WBC." (PMID 25403427, 2014). "Next, we sought to assess the expression of cancer-related genes, including BRCA1, at the mRNA level, in the WBC that harbor methylated BRCA1 promoter." (PMID 25403427, 2014). "MK-4827, also known as niraparib, is a novel 2-phenyl-2H-indazole-7-carboxamide PARP inhibitor that displayed anti-proliferation activities against BRCA1- and BRCA2-deficient cancer cells in vitro." (PMID 24795863, 2014). "The first was the observation that the size of indels was typically greater in BRCA1/2-inactivated cancers." (PMID 25093514, 2014). "Since, in our previous study, we have found a strong association between BRCA1 promoter methylation and young age (≤40 years) at diagnosis, it was crucial to screen for methylated BRCA1 promoter in cancer-free control cohort of young age." (PMID 25403427, 2014).
cancer (continued). "Of note, it has been demonstrated that PARPi, when combined with agents that impair DNA repair, are also effective in killing cancer cells containing wild-type BRCA1/2." (PMID 24962108, 2014). "Specifically, we examined the expression of Akt1m in primary cancers from BRCA1 conditional knockout mice (Brca1-/-), PtenG129E mutant females as well as transgenic mice that overexpress ERBB2 (MMTV-neu) and prolactin (NRL-PRL)." (PMID 24628780, 2014). "Mutations in common cancer genes such as PTEN, BRCA1, BRCA2, are also present but at much lower prevalence in HG-SC." (PMID 24675677, 2014). "Non-BRCA1/2 cancers have been reported to be distributed across the different molecular subtypes similar to the sporadic cancers; though several studies indicate an enrichment of the lumA subtypes among non-BRCA1/2 tumors compared to sporadic/unselected cases." (PMID 24479546, 2014). "Carrying an inherited mutation in the BRCA1 or BRCA2 gene increases a woman's lifetime risk of developing breast, ovarian and other cancers." (PMID 24698998, 2014). "BRCA1/2 somatic mutation or promoter methylation, ATM mutation, MRE11-dominant negative mutations in MMR-deficient cancers, FANCF promotor methylation and PTEN deficiency are all potential biomarkers of sensitivity to PARPi." (PMID 24616882, 2014). "This combined synthetic lethality is reminiscent of other drug interactions that have been described in cancer drug screens recently, such as the use of PARP inhibitors in tumors that have BRCA1/2 deficiency." (PMID 25594042, 2014). "Heterozygous mutation of BRCA1 or BRCA2 causes hereditary breast and ovarian cancer syndromes at an early age and increases the chance of bilateral cancers." (PMID 24317580, 2014). "Using the available RNAseq data, we correlated expression of BRCA1 with metabolite levels in the 23 TCGA cancers." (PMID 25091696, 2014). "Our results revealed that Aur A/B and BRCA1/2 are interactively suppressed to control the cancer cell growth and tumorigenesis through the regulation of the cell cycle progression, cytokinesis, and tetraploidy." (PMID 24775809, 2014). "In conclusion, the interplay of Aur A/B and BRCA1/2 constitutes a regulatory network in cancer development." (PMID 24775809, 2014). "In general, these studies found that BRCA1 and BRCA2 germline-mutated cancers harbored a greater number of break points and hence copy number changes." (PMID 25093514, 2014). "It is possible that ATM pathways are involved in upregulation of the PI3K/AKT pathway in BRCA1-defective cancer cells." (PMID 25426449, 2014). "Similar to cancer cells in which HDAC3 was depleted by shRNA, Hdac3-deficient MEFs also exhibited decreased expression levels of BRCA1 and ATR but increased levels of CHK1 and γ-H2AX." (PMID 25026298, 2014). "The variants found in four of the cancer genes APC, BRCA1, RET, and SDHB in our AJ centenarian sample had also been labeled as “almost certainly benign” in another sequencing study (ClinSeq) of 572 middle aged participants (17% of which are of AJ ancestry)." (PMID 25333069, 2014). "Between fertilization and reproductive age, are there any genetic changes in BRCA1+ carrier genome besides the cancer-targeted breast cell genome, considering the essential roles of BRCA1 in maintaining genome stability?" (PMID 24884718, 2014). "The actual culprit for cancer risk under such a scenario would, therefore, actually be the suppressive effect of low FMR1 alleles on BRCA1/2, converting anti-proliferative into a proliferative phenotypes." (PMID 25036526, 2014).
cancer (continued). "As stated, during DNA damage, BRCA1 expression was supposed to be at nucleus of cancer cells, at the site of the DNA damage." (PMID 25594033, 2014). "Among these 51 cancer genes, we find BRCA1 and BRCA2 that are multifunctional proteins playing a major role in DNA repair processes." (PMID 24550935, 2014). "BRCA1 and BRCA2 germline mutations are the fundamental defect in hereditary OC where the normal allele of the carrier is inactivated in cancer cells." (PMID 25136623, 2014). "Cancer patients treated with cisplatin, or those with low or intermediate levels of BRCA1 mRNA also attained a significantly better response, disease-free survival and overall survival than those with high levels." (PMID 24507701, 2014). "Similar defects were also displayed by BRCA1mut/+ fibroblasts, thereby supporting the notion that multiple factors combine to generate the tissue specificity of BRCA1-mutant cancer." (PMID 25400221, 2014). "Among the genes with rare variants in the most individuals are BRCA1, BRCA2, APC, MLL2, and MLL3, genes which are commonly mutated in cancers." (PMID 24728327, 2014). "In the case of BRCA1–2 mutant cancer cells, permanent inactivation of a DNA repair pathway offered the opportunity for therapeutic intervention based on the concept of synthetic lethality." (PMID 24618719, 2014). "The expression of BRCA1 in the carcinoma samples was significantly reduced compared with that observed in the benign tumors (P=0.031, Pearson’s χ2 test)." (PMID 24944674, 2014). "EGFR inhibition can reduce the expression of the BRCA1 protein, thereby making the cancer cells vulnerable to PARP inhibition." (PMID 24244833, 2013). "The increase of VEGF expression was shown also in the BRCA1-2 carrier compared to BRCAX cancers, suggesting its central part in BRCA1-2 related carcinomas." (PMID 23326384, 2013). "In some cancers BRCA1 downregulation occurs following the switch from the expression of 5′UTRa, which enables an efficient protein translation, to the expression of 5′UTRb, which, conversely, strongly inhibits translation." (PMID 23354980, 2013). "BRCA1-related cancers have distinct pathological features and are generally characterized by the lack of expression of human epidermal growth factor 2, estrogen, and progesterone receptors (triple negative breast cancer)." (PMID 23586058, 2013). "VEGF expression in BRCA1-2 carriers (HIS score 6) was significantly higher than in BRCAX cancers (HIS score 4) (p = 0.0001)." (PMID 23326384, 2013). "The percentage of nuclear HIF-1α expression was higher in the BRCA1-2 carriers than in BRCAX cancers (p<0.05), and in all familial than in sporadic tumor tissues (p = 0.0045)." (PMID 23326384, 2013). "Interest in these agents was heightened by the demonstration that BRCA1- and BRCA2- (BRCA1/2-) mutant cancer cells are selectively killed by single-agent PARP inhibitor treatment." (PMID 24062981, 2013). "Until recently, it was believed that mutations in the BRCA1 C-terminal (BRCT) domain led to reduced HR, resulting in genomic instability and, ultimately, the development of cancer." (PMID 23599763, 2013). "It is well known that BRCA1-2 carriers are tumors which are genetically different from sporadic cancers and they also have a different morphological phenotype." (PMID 23326384, 2013). "This review focuses on mechanistic aspects of the function of BRCA1 in HR repair following replication stress, and also the implications to tumor development and cancer therapy." (PMID 23388117, 2013). "With respect to the generation of malignancy, the DEABM recapitulated cancer incidences in both sporadic cancer and BRCA1 mutant simulations." (PMID 23704974, 2013). "We have previously shown that transiently exporting wt-BRCA1 protein from the nucleus (where DSBs are repaired) to the cytosol (where apoptosis is activated) makes cancer cells defective in the repair of DSBs." (PMID 23388100, 2013).